ENSG00000238295
Synonyms: LOC124906145
Gene: Small nucleolar RNA gene on chromosome 2 (177,345,858 to 177,345,961, reverse strand). Ensembl gene ENSG00000238295.
Gene Ontology:
Biological process: RNA processing
Cellular component: nucleolus
Homologues: Paralogues in human: SNORD13 (89% identical), SNORD13P1 (89% identical), SNORD13D (87% identical), SNORD13P3 (86% identical), SNORD13E (83% identical).